CHRND (cholinergic receptor nicotinic delta subunit)
Description:
After binding acetylcholine, the AChR responds by an extensive change in conformation that affects all subunits and leads to opening of an ion-conducting channel across the plasma membrane.
Synonyms: ACHRD; CMS2A; CMS3A; CMS3B; CMS3C; FCCMS; SCCMS
Tractability: Small molecule: an approved drug acts on it; a high-quality ligand is known; it belongs to a druggable protein family. Antibody: its Gene Ontology location is reachable by antibodies, with high confidence; UniProt places it where antibodies can reach, with medium confidence; UniProt predicts a signal peptide or a membrane-spanning region; the Human Protein Atlas places it where antibodies can reach. PROTAC: a small molecule that binds it is known.
Target class: Ion channel; Nicotinic acetylcholine receptor delta subunit; Nicotinic acetylcholine receptor; Ligand-gated ion channel
Gene: Protein-coding gene on chromosome 2 (232,525,993 to 232,536,667, forward strand). Ensembl gene ENSG00000135902.
Subcellular location: Postsynaptic cell membrane; Cell membrane
Subcellular location (Human Protein Atlas): Plasma membrane
Pathways (Reactome):
Neuronal System: Highly sodium permeable postsynaptic acetylcholine nicotinic receptors
Gene Ontology:
Molecular function: transmitter-gated monoatomic ion channel activity involved in regulation of postsynaptic membrane potential; acetylcholine receptor activity; acetylcholine-gated monoatomic cation-selective channel activity; acetylcholine binding; extracellular ligand-gated monoatomic ion channel activity; ligand-gated monoatomic ion channel activity; monoatomic ion channel activity; transmembrane signaling receptor activity
Biological process: musculoskeletal movement; skeletal muscle tissue growth; acetylcholine receptor signaling pathway; calcium ion transport; membrane depolarization; monoatomic ion transmembrane transport; muscle contraction; neuromuscular process; signal transduction; skeletal muscle contraction; synaptic transmission, cholinergic; chemical synaptic transmission, postsynaptic; excitatory postsynaptic potential; monoatomic cation transport; monoatomic ion transport; nervous system process; regulation of postsynaptic membrane potential
Cellular component: acetylcholine-gated channel complex; neuromuscular junction; plasma membrane; neuron projection; postsynaptic membrane; synapse; membrane; postsynaptic specialization membrane
Genetic constraint (gnomAD): Loss-of-function variants: 40 observed, 61.42 expected, observed/expected ratio (o/e) 0.65, 90% interval 0.5 to 0.85. The upper end of that interval is the gene's LOEUF score, 0.85, which puts it in group 3 of 6, group 1 being the genes least tolerant of losing a copy. Missense variants: 634 observed, 708.25 expected, observed/expected ratio (o/e) 0.9, 90% interval 0.84 to 0.96. Synonymous variants: 237 observed, 285.81 expected, observed/expected ratio (o/e) 0.83, 90% interval 0.75 to 0.92.
Homologues: Orthologues: chimpanzee CHRND (99% identical), macaque CHRND (98% identical), dog CHRND (92% identical), pig CHRND (91% identical), guinea pig CHRND (91% identical), mouse Chrnd (88% identical), rat Chrnd (88% identical), rabbit CHRND (87% identical), tropical clawed frog chrnd (68% identical), zebrafish chrnd (67% identical). Paralogues in human: CHRNG (45% identical), CHRNE (44% identical), CHRNB2 (39% identical), CHRNB4 (38% identical), CHRNB1 (38% identical), CHRNA4 (35% identical), CHRNA2 (35% identical), CHRNA3 (34% identical), CHRNA6 (34% identical), CHRNA1 (32% identical), CHRNB3 (32% identical), CHRNA5 (30% identical), and 33 more.
Diseases named in the same sentence as CHRND in open-access papers:
CHRND is named in the same sentence as 17 diseases in open-access papers, as found by Europe PMC text mining. Sharing a sentence is not in itself a finding about the gene and the disease. The quoted sentences say what the papers report.
congenital myasthenic syndrome (8 papers, 2017 to 2024). Congenital myasthenic syndrome (CMS) is a group of genetic disorders of impaired neuromuscular transmission at the motor endplate characterized by fatigable muscle weakness. "One patient had pathogenic variants in MAGEL2 and CHRND, which are diagnostic for Schaaf-Yang syndrome and congenital myasthenic syndrome, respectively." (PMID 37989827, 2024). "Mutations of CHRND gene in humans have been reported to be associated with congenital myasthenic syndrome." (PMID 33198087, 2020). "Moreover, four families with CM carried pathogenic variants in GFPT1, CHRNA1, or CHRND, all three previously associated with congenital myasthenia often involving muscle weakness similar to CM." (PMID 38982518, 2024). "In some cases, treatments such as acetylcholinesterase inhibitors may be considered, particularly in patients with pathogenic variants in congenital myasthenia genes (CHRNA1, CHRND, DPAGT1, and GFPT1)." (PMID 38982518, 2024). "For example, the CHRND (MIM 100720) gene, which can cause four main types of congenital myasthenic syndrome (CMS): LMPS (MIM 253290), slow-channel CMS (MIM 616321), fast-channel CMS (MIM 616322), and AChR deficiency CMS (MIM 616323), is encoded by the δ subunit." (PMID 36733345, 2023).
Alzheimer disease (1 paper, 2015). A progressive, neurodegenerative disease characterized by loss of function and death of nerve cells in several areas of the brain leading to loss of cognitive function such as memory and language. "Among the analysed target genes, nicotinic acetylcholine receptors (CHRNB3, CHRNE, CHRNB1, CHRND) were found, which are targets of drugs against Alzheimer's disease." (PMID 26693857, 2015).
Diabetes (1 paper, 2008). "We sequenced CHRNA1, CHRND and CHRNG in 24 Amish subjects from the Amish Family Diabetes Study (AFDS) and identified 20 variants." (PMID 18625075, 2008).
Escobar syndrome (1 paper, 2022). "While CHRNG mutations caused Escobar syndrome for 75 patients of known cases, a number of patients had a genetic etiology associated with variants in the TPM2, CHRND, CHRNA1, MUSK, MYH3, RAPSN, and DOK7 genes." (PMID 36292632, 2022). "Indeed, mutations in CHRNA1, CHRND, and TPM2 have been described to be associated with Escobar syndrome." (PMID 36292632, 2022).
Micrognathia (1 paper, 2023). Developmental hypoplasia of the mandible. "In conclusion, we have reported compound heterozygous variants apart from the variation spectrum of the CHRND (NM_000751.2) gene and a new diagnosis method for the early recognition of micrognathia, which is vital to provide appropriate genetic counseling to the parents." (PMID 36733345, 2023).
myasthenia (1 paper, 2026). "Although most of the patients with mutations in established CMS genes (such as DOK7, MUSK, RAPSYN, CHRNA1, CHRNB1, CHRND, and CHRNE) do not show cognitive symptoms, in some newly identified CMS subtypes, myasthenia is only one element of a more severe and complex clinical spectrum." (PMID 41575592, 2026).
nicotine dependence (1 paper, 2018). Physical and psychological dependence on nicotine. "Second, the neurotransmitter receptors in this pathway (including CHRNA5, CHRNA3, CHRNB4, and CHRND) participate in the biological process by which smoking induces nicotine dependence." (PMID 30104567, 2018).
rhabdomyosarcoma (1 paper, 2014). A rare aggressive malignant mesenchymal neoplasm arising from skeletal muscle. "Interestingly, CHRND, a member of the nicotinic acetylcholine receptor family, is a recognized candidate for tumor associated rearrangements and as one of the muscle-specific genes that is expressed in rhabdomyosarcomas." (PMID 24619124, 2014).
neuromuscular disease (2 papers, 2015). "Mutations were found in eight previously known neuromuscular disease genes (CHRND, CHNRG, ECEL1, GBE1, MTM1, MYH3, NEB and RYR1) and four novel neuromuscular disease genes (GPR126, KLHL40, KLHL41 and SPEG)." (PMID 26933539, 2015). "Within this cohort, mutations were found in eight previously known neuromuscular disease genes (CHRND, CHNRG, ECEL1, GBE1, MTM1, MYH3, NEB and RYR1) and four novel neuromuscular disease genes were identified and have been published as separate reports (GPR126, KLHL40, KLHL41 and SPEG)." (PMID 26578207, 2015).
tumor (2 papers, 2014 to 2019). "CHRNA5, CHRNA10, CHRNB4, CHRND, CHRNE, and CHRNG, however, were not expressed at levels significantly different from the non-tumor control samples." (PMID 31590360, 2019).
CHRND also shares sentences with these, for which no sentence is quoted: arthrogryposis (2 papers); brain malformations (1); channelopathies (1); epilepsy (1); Intellectual disability (1); multiple pterygium syndrome (1); Schaaf-Yang syndrome (1).